NLRP3 (NLR family pyrin domain containing 3)
Diseases named in the same sentence as NLRP3 in open-access papers (continued):
Sharing a sentence is not in itself a finding about the gene and the disease.
leukemia (continued). "Thus, we sought to assess the expression profiles of NLRP3, CASP1, and IL‐1β in pediatric blood cancer samples, reasoning that the largest therapeutic impact of NLRP3 inhibition on cancer progression likely occurs in leukemia subtypes with the highest expression levels." (PMID 40104043, 2025). "Although this inhibitory effect of caspase-1 on autophagy has only been demonstrated in Prion disease and during Pseudomonas aeruginosa infection, it might also be involved in the pathogenicity of leukemia, which is characterized by high NLRP3 activity and IL-1β secretion." (PMID 33525345, 2021). "Furthermore, we examine a connection between NLRP3, autophagy and leukemia." (PMID 33525345, 2021). "However, the previously summarized research findings on this topic suggest that certain types of leukemia may benefit from modifying the NLRP3 inflammasome pathway." (PMID 33525345, 2021). "A role for ROS in general for NLRP3 inflammasome activation was demonstrated in an elegant study by Zhou and colleagues showing that the NLRP3 inflammasome can be activated through direct treatment of the human leukemia-derived macrophage-like cell line THP-1 (THP-1) with H2O2." (PMID 33669824, 2021). "Interestingly, the comparison of NLRP3 and Caspase 1 expression between glucocorticoid sensitive and resistant primary leukemia cells isolated from 444 patients shows that high expression of Caspase 1 and NLRP3 is associated with an increase in glucocorticoid resistance." (PMID 33716981, 2021). "Specifically, expression analysis revealed increased NLRP3 expression in pediatric BCP‐ALL and MLL‐ALL PDX samples compared to the other five leukemia subtypes analyzed, with T‐ALL exhibiting the lowest expression level." (PMID 40104043, 2025). "The comparison revealed consistent trends, with BCP‐ALL and MLL‐ALL bearing the highest NLRP3 expression, T‐ALL exhibiting the lowest IL‐1β expression and a persistent increase in CASP1 expression across the leukemia panel." (PMID 40104043, 2025). "Compared to other types of leukemia, CLL patients display diminished expression levels of NLRP3, coupled with elevated GSDM-E." (PMID 38730609, 2024). "We focused on NLRP3 and/or the AIM2 inflammasome because the cluster 9 cells from our scRNA-seq analysis of Usp18+/Δ primary murine leukemia cells predicted inflammasome activation." (PMID 36646704, 2023). "The result showed that NLRP3 overexpression increased the IC50 of ADR in U937 leukemia cells (from 114.03 to 143.06 μg/L), indicating the response to ADR was inhibited by increased NLRP3 expression and activation." (PMID 34211462, 2021). "We showed that NLRP3 inflammasome is over-expressed and highly activated in AML bone marrow leukemia cells, which is correlated with poor prognosis." (PMID 34211462, 2021). "As caspase-1 is pivotal for the activation of NLRP3 inflammasome, we treated primary AML leukemia cells with caspase-1 inhibitor Z-YVAD-FMK." (PMID 34211462, 2021). "For example, glucocorticoid‐resistant leukemia cells were found to overexpress NLRP3 and CASP1, suggesting that targeting NLRP3‐signaling pathways could improve response rates, particularly in treatment‐resistant diseases." (PMID 40104043, 2025). "In patient-derived samples, NLRP3 was overexpressed and highly activated in AML bone marrow leukemia cells, and this correlated with poor prognosis, and the activation of NLRP3 in AML cells promoted leukemia cell proliferation, inhibited apoptosis, and increased resistance to chemotherapy." (PMID 34769275, 2021). "Activation of alternative pathways, such as KRAS/RAC1/ROS/NLRP3, in leukemia cells or non-hematopoietic cells may also lead to the production of pro-inflammatory IL-1β that promotes leukemia cell proliferation in an autocrine fashion." (PMID 35460465, 2022).
leukemia (continued). "In addition, recent data also indicate that the NLRP3 inflammasome plays an important role in hematological malignancies, as in, for example, myelodysplastic syndrome (MDS), myeloproliferative neoplasms (MPNs) and leukemia." (PMID 33525345, 2021). "Interestingly, exposure of human leukemia monocytic cells to Aedes aegypti salivary gland extract results in the downregulation of innate immune, antiviral, and inflammatory-related genes, including NF-kB, IFN-β, NLRP3, and subsequently IL-1β and IL-6, among others, at 24–36 hours." (PMID 40272158, 2025).
mastitis (39 papers, 2018 to 2026). Inflammation of breast tissue during lactation or postpartum due to an obstructed duct or infection. "BMECs have immune activity and can activate NLRP3 inflammatory mediators during mastitis, and then the activated NLRP3 inflammasome causes pyroptosis, thereby releasing proinflammatory cytokines and further expanding the inflammatory response." (PMID 39451217, 2024). "Increased TLR4 levels were detected in the colon and mammary gland of AN mice, accompanied by enhanced downstream NF-κB and NLRP3 pathways, which are involved in mastitis pathogenesis and other gut dysbiosis-associated diseases." (PMID 37069691, 2023). "Collectively, these data implicated miR-223 as modulating the NLRP3 inflammasome and Keap1-medidated oxidative stress pathway in experimental mastitis." (PMID 37710276, 2023). "DCA-mediated TGR5 activation inhibited the NF-κB and NLRP3 pathways and mastitis caused by S. aureus via activating cAMP and PKA." (PMID 36755021, 2023). "Low-grade endotoxemia impaired host ALP by activating Neu, causing persistent injury and mastitis by activating the TLR4-cGAS-STING-NF-κB/NLRP3 signatures." (PMID 36451232, 2022). "Both NF-κB and NLRP3 activation are critically implicated in the pathogenesis of mastitis." (PMID 41466496, 2025). "Pathway enrichment analysis indicated that NLRP3, caspase-1 (CASP1), and GSDMD were enriched in the NOD-like receptor signaling pathway and were closely associated with mastitis." (PMID 41897529, 2026). "Studies have shown that PS can effectively alleviate Staphylococcus aureus-induced mastitis by inhibiting the activation of pro-inflammatory signaling pathways such as NF-κB/NLRP3, reducing the release of inflammatory factors such as IL-1β and TNF-α." (PMID 41596521, 2026). "Third, mastitis shares essential inflammatory pathways such as NF-κB, the NLRP3 inflammasome, and MAPK with other inflammatory conditions." (PMID 40559831, 2025). "Once there, these mEVs activate the cGAS-STING-NF-κB/NLRP3 signaling pathway, ultimately inducing mastitis." (PMID 41466496, 2025). "The mechanistic pathway involves healthy gut microbiota converting CA to DCA, leading to TGR5 activation, cAMP-PKA signaling, inhibition of NF-κB/NLRP3 pathways, and ultimately reduced inflammation and mastitis protection." (PMID 41295688, 2025). "We propose that these mEVs reach the mammary gland, where their microbial DNA cargo activates the cGAS-STING pathway, subsequently triggering the NF-κB and NLRP3 inflammasome axes, ultimately inducing mastitis." (PMID 41466496, 2025). "Deoxycholic acid-mediated activation of the G protein-coupled receptor reduces inflammation by inhibiting the NF-κB and NLRP3 pathways and improves the integrity of the blood-milk barrier, thereby reducing mastitis." (PMID 40552082, 2025). "In the mammary gland, repeated LPS exposure also impairs ALP activity, thereby contributing to mastitis through activation of the TLR4-cGAS-STING-NF-κB/NLRP3 pathway." (PMID 41139776, 2025). "NLRP3 inflammasome activation in subclinical mastitis and after LTA stimulation in MAC-T cells and murine mammary glands was confirmed in the present study by the upregulation of NLRP3, ASC, cleaved-caspase-1 and IL-1β." (PMID 39765775, 2024). "The ROS/autophagy/NLRP3 inflammasome axis was identified as a promising target for treating subclinical bovine mastitis in this study." (PMID 39765775, 2024). "Unfortunately, the modulating effect of autophagy on the NLRP3 inflammasome in subclinical bovine mastitis is still elusive." (PMID 39765775, 2024). "For example, gut microbiota-mediated secondary bile acid (deoxycholic acid (DCA)) can alleviate Staphylococcus aureus-induced mastitis by inhibiting NLRP3 inflammasome activation." (PMID 39334766, 2024).
mastitis (continued). "Supplementing with selenium was shown to significantly curtail the expression of NLRP3 inflammasome and proinflammatory cytokines IL-1β/IL-18, thereby mitigating the abnormal inflammatory response and consequently preventing mastitis in mice." (PMID 38259482, 2023). "For example, SCFA, particularly butyrate, can limit the activation of NF-κB and NLRP3 pathways, which were involved in the pathogenesis of mastitis and responsible for the production of inflammatory cytokine." (PMID 36656870, 2023). "Increased LPS and systemic inflammation subsequently disrupt the blood-milk barrier and facilitate the development of mastitis through TLR4-NF-κB/NLRP3 signatures." (PMID 37069691, 2023). "Collectively, these results indicated that DCA alleviated S. aureus-induced mastitis through the TGR5-cAMP-PKA-NF-κB/NLRP3 axis." (PMID 36755021, 2023). "Then, our objective was to emphasize the role of miR-223 in regulation of the NLRP3 inflammasome and Keap1/Nrf2 oxidative stress pathway in mastitis models involving LPS treatment of bMECs and murine mammary glands." (PMID 37710276, 2023). "Treatment with DCA alleviates S. aureus-induced mastitis in mice and the underlying mechanism is involved in the activation of TGR5, which inhibits the activation of NF-κB and NLRP3 signaling by cAMP and PKA." (PMID 36755021, 2023). "Research indicates that inhibition of NLRP3 inflammasome activation evidently ameliorates the severity of mastitis." (PMID 36362066, 2022). "Exposure to LPS has been reported to induce mtDNA synthesis through Toll-like receptor (TLR)-4, which is also involved in the activation of the NF-κB and NLRP3 pathways and mastitis pathogenesis." (PMID 36451232, 2022). "Our work provides insight into the potential role of NLRP3 in the molecular pathogenesis of S. aureus mastitis and contributes to the elucidation of the molecular basis of S. aureus mastitis pathogenesis." (PMID 35123552, 2022). "An increase in inflammatory cytokine production occurred due to the activation of proinflammatory pathways, such as NF-κB and NLRP3, which have been reported to play central roles in the pathogenesis of mastitis." (PMID 36451232, 2022). "Our previous study has demonstrated that decreased autophagy-related protein expression level and increased IL-1β and NLRP3 inflammasome-related protein expression level are involved in the pathogenesis of mastitis." (PMID 36362066, 2022). "In summary, our study demonstrates that Z. morio hemolymph can alleviate inflammatory response through inhibiting NLRP3 inflammasome activation and enhancing autophagy activity, as well as repairing the blood–milk barrier to relieve E. coli–induced mastitis." (PMID 36362066, 2022). "Increased inflammatory cytokines are processed by host signaling transduction, such as NLRP3 and NF-κB, which have been widely proven to be involved in the pathogenesis of mastitis." (PMID 36451232, 2022). "Our results reveal that Z. morio hemolymph alleviates E. coli-induced mastitis via lessening the inflammatory response by regulating the NLRP3 and ATG5/ATG16L1 signaling pathway, as well as repairing the blood-milk barrier." (PMID 36362066, 2022). "The data also showed that SYK gene expression and protein levels have a strong consistency in bovine mastitis, and NLRP3, TLR4 and IL-1β as well." (PMID 36672605, 2022). "RMT from mastitis cows (M-RMT) to recipient mice transferred mastitis symptoms through the LPS-mediated TLR4-cGAS-STING-NF-κB/NLRP3 pathways." (PMID 36451232, 2022). "They showed that NLRP3 expression and caspase-1 were increased during E. coli infection, while L. rhamnosus GR-1 pretreatment ameliorated E. coli-induced mastitis." (PMID 34835501, 2021). "Actually, change in pharmacodynamics of MAF in this mastitis model needs to be evaluated in the presence of specific antagonist of NLRP3 inflammasome or NF-ĸB." (PMID 33981236, 2021).
mastitis (continued). "NLRP3 inflammasome and pyroptosis play important roles in the pathogenesis of many inflammatory diseases, including mastitis." (PMID 33488936, 2020). "However, excessive activation of the NLRP3 inflammasome can lead to tissue damage and immune dysfunction, contributing to the onset and progression of inflammatory diseases such as mastitis." (PMID 40243637, 2025). "Although the combined inhibitory effects of QA and ICAB on NF-κB and NLRP3 pathways found in this study, further investigations are need on the mechanisms underlying QA and ICAB combination effects and the application in mastitis prevention and treatment." (PMID 40538727, 2025). "Previous study demonstrated that inhibition of NLRP3 inflammasome could attenuate S. aureus-induced mastitis." (PMID 41170435, 2025). "Furthermore, inhibition of miR-223 enhanced pathology of murine mastitis and increased expression of NLRP3 protein, consistent with previous studies in cattle." (PMID 37710276, 2023). "Toll-like receptor (TLR)-4 is known to be responsible for the recognition of LPS, and thus mediates proinflammatory cytokine production by activating inflammatory signatures, such as NF-κB and NLRP3, which have been shown to participate in the pathogenesis of mastitis." (PMID 37069691, 2023). "Ruminal microbiota transplantation from mastitis cows (M-RMT) to mice induced mastitis symptoms in recipient mice along with increased mammary proinflammatory signature activation of the TLR4-cGAS-STING-NF-κB/NLRP3 pathways." (PMID 36451232, 2022). "Moreover, SYK protein level was also significantly down-regulated in bovine mastitis tissue, and protein levels of NLRP3, TLR4 and IL-1β were significantly up-regulated." (PMID 36672605, 2022). "Together, NLRP3 inflammasome can be a potential therapeutic target for mastitis." (PMID 36362066, 2022). "Moreover, dioscin also can reduce the production of proinflammatory factors such as interleukin-1 beta (IL-1β) and inhibit the activation of NLRP3 inflammasome in LPS-induced mice mastitis." (PMID 33488936, 2020). "This study aimed to investigate whether XIST played a critical role in regulating the inflammatory response to pathogenic stimulus through NF‐κB pathway and further identify the relationship between NF‐κB pathway and NLRP3 inflammasome in bovine mastitis." (PMID 30362186, 2019). "Previous studies have shown that mangiferin can inhibit mastitis induced by LPS via suppressing NF-κB and NLRP3 signaling pathways, and resveratrol inhibits LPS-induced mice mastitis through attenuating the Mitogen-activated protein kinase (MAPK) and NF-κB signaling pathway." (PMID 30200569, 2018). "Notably, our results contrast with studies focusing on plant-derived anti-inflammatory compounds (e.g., curcumin, resveratrol) for mastitis, which often act through similar NF-κB/NLRP3 pathways but face challenges such as poor bioavailability or inconsistent gut absorption." (PMID 41170435, 2025). "However, the relationship involving NLRP3 inflammasome, autophagy, and ROS in subclinical bovine mastitis is still unknown." (PMID 39765775, 2024). "Therefore, our objective was to determine the role of miR-223 in regulation of the NLRP3 inflammasome and Keap1/Nrf2 oxidative stress pathway in mastitis models involving LPS treatment of immortalized bovine mammary epithelial cells (bMECs) and murine mammary glands." (PMID 37710276, 2023). "However, the mechanism via which mitophagy regulates the NLRP3 inflammasome in breast diseases, especially during mastitis, remains unknown." (PMID 34594329, 2021). "Thus, our finding suggested that sodium butyrate relieved LPS-induced inflammatory responses in bovine macrophage by inhibiting the canonical NF-κB, NLRP3 signaling pathway, and histone decetylation, which might be helpful to prevent cow mastitis." (PMID 33251265, 2020).
mastitis (continued). "Our findings identify NLRP3 and NLRC4 inflammasomes as potential targets for bovine mastitis therapy and could strengthen the development for other inflammasome-targeted therapies in E. coli-associated mastitis." (PMID 30087667, 2018). "Treatment of mice with hexadecanamide and phytosphingosine alleviates S. aureus-induced mastitis by regulating the PPARα-SIRT1-NF-κB and NLRP3 pathways, respectively." (PMID 41139776, 2025). "The results demonstrated that CB significantly alleviated LPS-induced mastitis by downregulating the expression of pro-inflammatory factors IL-1β, TNF-α, and the NLRP3 inflammasome while also reducing cell apoptosis." (PMID 40243637, 2025). "Therefore, although the role of piRNAs in mastitis remains ambiguous, their established functions in regulating cytokine secretion, NLRP3 inflammasome expression, and NF-κB signaling in other inflammatory disorders suggest that piRNAs may similarly influence mastitis progression." (PMID 40559831, 2025). "In summary, these findings suggest that SEV induces mastitis in mice, activates the cGAS-STING-NF-κB/NLRP3 pathway, and disrupts the integrity of the mammary barrier." (PMID 41466496, 2025). "In conclusion, these results suggest that the cGAS-STING-NF-κB/NLRP3 signaling pathways is activated in both HCD-induced goats and HC-RMT mice, contributing to the development of mastitis." (PMID 41466496, 2025). "According to Western blotting results, the mammary gland with subclinical bovine mastitis exhibited obviously increased protein expressions concerning ASC, cleaved-caspase-1, NLRP3, and IL-1β compared with the healthy ones." (PMID 39765775, 2024). "In the cell model of bovine S. aureus mastitis, the S. aureus adhesion to epithelial cells can be mediated by lncRNAs TUB and H19, and the NF-κB/NLRP3 inflammasome pathway is regulated by the lncRNA XIST." (PMID 34895356, 2021). "Notably, CB treatment in MAC-T cells and mouse mastitis models markedly reduced the expression of IL-1β, TNF-α, and NLRP3, indicating potent anti-inflammatory effects similar to those observed with other natural compounds such as allicin and lentinan." (PMID 40243637, 2025). "Although miR-223 mitigated inflammation and prevented collateral damage during infection and inflammation, its function and regulation in response to NLRP3 or Keap1 treatment in bovine mastitis have not been well characterized." (PMID 37710276, 2023). "Supplementation of the mice with DCA, but not CA, attenuated S. aureus-associated mastitis by limiting inflammatory responses and improving the blood-milk barrier disruption in which the underlying mechanism was involved in TGR5-mediated NF-κB and NLRP3 inhibition through the cAMP-PKA pathways." (PMID 36755021, 2023).